PLOD2 (procollagen-lysine,2-oxoglutarate 5-dioxygenase 2)
Diseases named in the same sentence as PLOD2 in open-access papers (continued):
Sharing a sentence is not in itself a finding about the gene and the disease.
tumor (continued). "Previous research has found that PLOD2 expression is remarkably correlated to tumor size and DFS in HCC patients." (PMID 33014843, 2020). "The PLOD2 over expressed GC cases had also increased collagen expression in their tumor tissues which showed HIF1A/PLOD2 signaling pathway as a regulator of GC aggressiveness in a collagen-related status." (PMID 32467737, 2020). "When BC cell lines cocultured with mature adipocytes, adipocyte-derived leptin and IL-6 promoted local invasion and eventually metastasis of tumor cells via activation of lysyl hydroxylase 2 (PLOD2)." (PMID 32787888, 2020). "We further proved that the high expression levels of PLOD1 and PLOD2 were markedly correlated with higher tumor grade." (PMID 33014843, 2020). "HIF-1 facilitates ECM remodeling through upregulating expression of P4HA1, P4HA2, and PLOD2 in hypoxic fibroblasts, which results in tumor invasion and metastasis." (PMID 33299876, 2020). "By calculating the proportion of immuno-staining with high, medium, low, or not detected in different cancer types as reported by HPA, we found DDX27 and PLOD2 showing medium to high tumor-specific staining in multiple cancer types." (PMID 33287876, 2020). "The high expression levels of PLOD1 and PLOD2 genes were significantly correlated with higher tumor grades in HCC patients." (PMID 33014843, 2020). "The published reports suggest that PLOD2 plays a key role in collagen cross-linking, promoting tumor cell invasion and migration." (PMID 31455288, 2019). "Given that our above results showed that tumor-derived PAI-1 stimulated adipocyte-derived collagen reorganization via upregulation of PLOD2 expression." (PMID 31170987, 2019). "PLOD2 and another collagen cross-linking enzyme, lysyl oxidase homolog-2, were shown to be epigenetically regulated by the tumor-suppressive microRNAs miR-26a and miR-26b and to promote metastasis in RCC." (PMID 31446433, 2019). "In contrast, PLOD2 protein was present in both normal and ccRCC tissues, but the expression level was much higher in the tumor sections." (PMID 31446433, 2019). "In vitro, we also found that PLOD2 overexpression in Hep-2 and FaDu cells strongly promoted tumor sphere formation." (PMID 31455288, 2019). "It was worthy to investigate the role of PLOD2-mediated structural changes of adipose-derived collagen on the regulation of distal organ seeding and growth of metastatic tumor cells in vivo." (PMID 31170987, 2019). "As functional studies have shown, PLOD2 hydroxylates telopeptidyl lysine residues on collagen, lowers levels of lysine aldehyde-derived cross-links, increases tumor stiffness, and enhances tumor cell invasion and metastasis." (PMID 31455288, 2019). "The function of PLOD2 in the collagen cross-link switch and tumor cell invasion and migration has been confirmed in relation to metastasis." (PMID 31455288, 2019). "Treatment with shPLOD2 plus DDP resulted in a significant reduction in tumor growth; however, compared with the control, PLOD2 overexpression resulted in a significant increase in tumor growth." (PMID 31455288, 2019). "Our results showed that adipocyte-derived IL-6 and leptin stimulate the migration of tumor cells via upregulation of PLOD2 expression." (PMID 30563531, 2018). "PLOD2 depletion significantly inhibited the migration of MDA-MB-231 tumor cells cocultured with adipocytes." (PMID 30563531, 2018). "PLOD2 is highly expressed in CAFs; silencing PLOD2 expression in CAFs significantly reduced the tumor invasion and metastasis." (PMID 30003082, 2018). "The clinical significance of PLOD2 in samples from different stages status was further evaluated by IHC analysis in a tumor tissue microarray." (PMID 30563531, 2018). "Immunohistochemical staining for PLOD2 confirmed that knockdown of PLOD2 decreased tumor PLOD2 protein expression." (PMID 30563531, 2018). "Since multiple steps are involved in the formation of tumor fibrosis, PLOD2 and P4HA also mediate essential sections of metastasis." (PMID 29472856, 2018).
tumor (continued). "PLOD2 inhibition not only affects the cancer cells themselves, but it also impacts on the tumor microenvironment, thus impairing metastasis." (PMID 29165393, 2017). "Of these genes, PLOD2 expression has been significantly correlated with tumor size and macroscopic intrahepatic metastasis and has also been identified as a significant, independent factor of poor prognosis." (PMID 29117265, 2017). "The results indicated that PLOD2 promoted cross-linking of collagen fibers around tumor cells and increased tumor stiffness." (PMID 28423580, 2017). "Meanwhile, the clinical sample analysis also showed that the expression of PLOD2 was higher in tumor tissue than in normal tissue." (PMID 29072684, 2017). "Next, we analyzed expression data from the REMBRANDT database for PLOD2 based on tumor grade (n = 178)." (PMID 28423580, 2017). "Third, stiffness measurements made with compression and indentation tests demonstrated that knockdown of PLOD2 reduced tumor stiffness (P < 0.05)." (PMID 28423580, 2017). "Consistent with the finding in the tumor samples, ECM components and mechanics-associated genes (from PLOD2 to ICAM1) were upregulated in ccRCC patients as shown by the ‘TME PCR Array’." (PMID 28846080, 2017). "Specifically, the up-regulation of PLOD2 in tumour cells and tumour stromal fibroblasts changes collagen cross-linking tumour stroma to form aligned and stiff collagen fibres." (PMID 28507454, 2017). "In this model, we found that in the metastasis nodule in the liver, control tumors showed extensive invasion into the adjacent tissue, whereas PLOD2-knockdown tumors maintained a distinct tumor–stroma boundary." (PMID 28410212, 2017). "Up-regulation of PLOD2 protein was confirmed in 7 tumor samples and 6 normal samples by western blot analysis (P < 0.001)." (PMID 28410212, 2017). "To explore the role of PLOD2 in tumor growth in vivo, we established a xenograft mouse model." (PMID 41584042, 2026). "Targeting PLOD2 may offer a novel strategy to enhance therapeutic responses, particularly for those with elevated PBRM1 mutations or hypoxic tumor microenvironments." (PMID 41584042, 2026). "Additionally, in a mouse model of lung adenocarcinoma, collagen cross-linking mediated by PLOD2 expressed by CAFs was found to enhance tumor invasiveness." (PMID 40211368, 2025). "Conversely, Plod2, Cdc20, and Cct5 genes were significantly upregulated in tumor tissues." (PMID 40018995, 2025). "Notably, several of these enzymes are druggable: for example, PLOD1 and PLOD2, which are involved in collagen crosslinking, can be targeted by specific inhibitors such as minoxidil, which disrupts collagen maturation and tumor-stroma interactions." (PMID 40034261, 2025). "In addition, PLOD2 silencing reduced tumor progression and stemness in CDDP-resistant LC cells by suppressing P-gp and MRP1 through Integrin β1." (PMID 38741195, 2024). "PLOD2 enhances tumor metastasis by inducing Integrin β1 hydroxylation." (PMID 38741195, 2024). "Our research indicates that PLOD2 + SAA1 + tumor cells might be capable of communicating with tumor-associated macrophages (TAMs) through specific ligand-receptor pairs, such as MIF-(CD74 + CXCR4), MDK-LRP1 and C3-C3AR1." (PMID 38951896, 2024). "Due to an inappropriate regulation of the plods family in tumors, PLOD2 triggers extracellular matrix (ECM) collagen remodeling in the tumor microenvironment (TME), and as a result of increased collagen content in solid tumors, tumor infiltration, invasion, and distant metastasis are fostered." (PMID 39769264, 2024). "Moreover, our investigation of single-cell RNA datasets revealed that tumor cells expressing high levels of PLOD2 and SAA1 exhibited enhanced malignancy, as indicated by elevated MECRGS scores, stemness, and copy number variations (CNVs)." (PMID 38951896, 2024). "The PLOD2 + SAA1 + tumor cells could communicate with other cells through ligand-receptor pairs like SPP1-CD44, MIF-(CD74 + CXCR4), and MDK-LRP1." (PMID 38951896, 2024).
tumor (continued). "Our study revealed that PLOD2 could promote ccRCC cell proliferation, migration, tumor formation, and metastasis." (PMID 38008826, 2023). "Further investigation was performed in the xenograft mouse model to determine whether PLOD2 contributes to tumor growth." (PMID 38008826, 2023). "To determine the role of PLOD2 in tumor metastasis, we established an OS lung metastasis model." (PMID 36276118, 2022). "Additionally, tumor-released plasminogen activator inhibitor-1 (PAI-1) can induce PLOD2 expression in adipocytes, followed by collagen reorganization at the tumor-adipose periphery." (PMID 36361914, 2022). "PLOD2 knock-down inhibited tumor proliferation, invasion and anchorage-independent growth." (PMID 35682709, 2022). "As an important modulator of the extracellular matrix and TME, PLOD2 may also activate the tumor-infiltrating neutrophils." (PMID 35682709, 2022). "Therefore, for the first time, we detected the spatial expression patterns of PLOD2 in tumor cells (TCs), fibroblast-like cells (FLCs) and tumor-infiltrating lymphocytes (TILs) in a cohort of 100 OSCC patients." (PMID 34944486, 2021). "Furthermore, we also performed many in vitro experiments to confirm that PLOD2 exerted tumor promoter effects by promoting tumor proliferation and migration." (PMID 34179084, 2021). "Moreover, our previous results exhibited that m6A methylation of PLOD2 in 3′’-untranslated regions increased remarkably in five tumor tissues compared to their paired adjacent normal tissues." (PMID 34179084, 2021). "A significant increase in m6A modification in PLOD2 mRNA was observed in tumor samples." (PMID 34179084, 2021). "Finally, we studied the correlation between PLOD2 and tumor-infiltrating immune cells in the tumor microenvironment." (PMID 34258263, 2021). "In addition, FLCs induce collagen cross-linking switch in tumor stroma through PLOD2, thus affecting the invasiveness of tumor cells." (PMID 34944486, 2021). "Upon secretion cytokine analysis, adipocyte-derived IL-6 or tumor-derived PAI-1 might exert roles in activating PLOD2 in CAAs." (PMID 31170987, 2019). "Moreover, we found that silencing PLOD2 strongly inhibited Hep-2 and FaDu tumor sphere formation, generating approximately 2-fold fewer spheres with an approximately 2-fold lower cell content compared with that in the control cells." (PMID 31455288, 2019). "Moreover, immunohistochemistry staining showed that PLOD2 was higher expression in the adipose tissues at the tumor periphery than adipose tissues grown alone (right)." (PMID 31170987, 2019). "Further, PLOD2 knockdown correlated with decreased tumor weight." (PMID 30563531, 2018). "Increased PLOD2 expression is crucial for tumor invasion and metastasis." (PMID 30003082, 2018). "Knockdown of PLOD2 in pancreatic stellate cells inhibits directional migration of cancer cells within the matrices by constructing an insensitive microenvironment of three-dimensional (3D) matrices to tumor migration." (PMID 30003082, 2018). "c Representative immunohistochemical images for PLOD2 expression in tumor tissues." (PMID 30563531, 2018). "After 3 days, tumor cells were harvested and PLOD2 protein expression was detected." (PMID 30563531, 2018). "We next sought to identify molecular pathways that might mediate the involvement of PLOD2 in tumor cell migration and invasion." (PMID 28423580, 2017). "Among the PLOD genes, PLOD2 contributes to tumor angiogenesis and cancer prognosis." (PMID 26033187, 2015). "Additionally, a strong correlation was detected between PLOD2 and DCLK1-L in the tumor samples of this ccRCC cohort (r = 0.7640, p = 0.0009), which was further supported by significant coexpression of PLOD2 and DCLK1 isoform 1 and isoform 2 in the TCGA ccRCC cohort." (PMID 40775208, 2025).
tumor (continued). "Additionally, we discovered a distinct ccRCC tumor cell subtype characterized by the high expressions of PLOD2 (procollagen-lysine,2-oxoglutarate 5-dioxygenase 2) and SAA1 (Serum Amyloid A1), which we further validated in the Renji tissue microarray (TMA) cohort." (PMID 38951896, 2024). "To determine whether LH2 influences intra-tumoral immunity, we quantified immune cell subsets in subcutaneous tumors generated by Plod2 KO or parental 344SQ cells and identified alterations in T cell and myeloid cell subsets that were consistent with an anti-tumor response in Plod2 KO tumors." (PMID 33875777, 2021). "Indeed, PLOD2/3 had been reported to be crucial for tumor invasion and metastasis." (PMID 33134376, 2020). "Consistently, we validated not only that the level of PLOD2 protein expression was upregulated in the LSCC tissues compared with that in the paired adjacent normal tissues by the IHC staining of 114 archived LSCC tissues but also that PLOD2 expression increased along with tumor progression." (PMID 31455288, 2019). "Moreover, PLOD2 participates in tumour cell-microenvironment communication." (PMID 28507454, 2017). "The apparent downregulation of NIP3, Aldolase C, PLOD2 and other hypoxia-inducible genes on the in vivo array in all tumour samples, even in tumours where hypoxia and necrosis were present, may represent a relative basal upregulation of these genes in the monolayer cell culture panel." (PMID 16052224, 2005). "Hypoxia has been found to induce expression of the protein PLOD2 in RCC via transcriptional activation by HIF1a; leading to downstream AKT activation and tumor progression." (PMID 39410010, 2024). "Among these six hub genes, DEPTOR, DPEP1, NAT8, and SUSD2 were expressed at their highest levels in normal tissues, whereas PLOD2 and SLC7A5 were expressed at their highest levels in tumor thrombi." (PMID 37328520, 2023). "In the hypoxic tumor microenvironment, the transcriptional regulation of HIF1A mediates the upregulation of PLOD2, which can activate EGFR phosphorylation, thereby activating the downstream AKT-mTOR pathway and ultimately promoting ccRCC tumor progression." (PMID 38008826, 2023). "The expression levels of SMS, ASNS, PLOD2, P4HA1, PAH, and KYNU were upregulated in tumor samples compared with normal samples, and the remaining three genes were downregulated." (PMID 37511510, 2023). "The interference of the expression levels of SMS, P4HA1, PAH, PLOD2, and KYNU significantly decreased the invasion of tumor cells." (PMID 37511510, 2023). "PLOD1, PLOD2, and PLOD3 were highly expressed in LGG tumor tissues compared to normal tissues (p < 0.01)." (PMID 35250490, 2022). "It was found that LOXL2, PLOD2, MMP14 and SPOCK1 were upregulated in tumor samples, whereas DCN was downregulated in tumor specimens." (PMID 36186418, 2022). "Compared with normal kidney tissues, antibody stainings for ANKZF1, CD44, IDUA, KIF20A, PLOD2, and VCAN were high in ccRCC tumor tissues, whereas they were low for CHST6, HS6ST2, NDST3 and FBP1." (PMID 33836688, 2021). "As reported, miR-26b-5p is a tumor suppressor and modulator in cell cycle regulation that targets different genes, including CCND2, PLOD2, JAG1, MAP3K9 and KPN2." (PMID 34488538, 2021). "In addition, some reported natural compounds that are suppressors of PLOD2 expression, such as minoxidil and berberine, were shown to inhibit cancer cell migration, reverse the switch in the formation of collagen cross-links and suppress metastasis in certain tumor types." (PMID 33805564, 2021). "PLOD2 is regulated by HIF-1α, TGF-β1, and microRNA-26a/b through the PI3K-AKT or the TGF-β/Smad signaling pathways in tumor cells." (PMID 33495412, 2021). "Multiple genes, such as FBP1, PLOD2, VCAN, and CD44 have been demonstrated to participate in epithelial-mesenchymal transition (EMT) promotion of tumor metastasis." (PMID 33836688, 2021).
tumor (continued). "Western blot results showed that FN1(11/12),LTBP1(11/12), PLOD2(11/12), RCN3(10/12), THBS1(11/12) were increased in tumor tissues (Paired-samples t-test, p < 0.05), indicating that the screening results of TMT technology were credible." (PMID 32216815, 2020). "Tumor-derived PAI-1 was required to activate the expression of the intracellular enzyme procollagen-lysine, 2-oxoglutarate 5-dioxygenase 2 (PLOD2) in CAAs." (PMID 31170987, 2019). "Tumor aggressiveness stimulated by HIF-1α has been found to rely on collagen remodeling enzymes, including PLOD2, and the prolyl hydroxylases, but PLOD3 is poorly studied." (PMID 29644003, 2018). "Interestingly, high expression of 4 genes targeted by anti-tumor miRNAs was significantly associated with poor prognosis of patients with RCC according to TCGA database analyses (UHRF1: p = 4.87E-06, LOXL2: p = 0.0343, PLOD2: p = 0.000855 and SKA1: p = 1.44E-07)." (PMID 29928475, 2018). "Our findings show that PLOD2 is not merely a passive gene but an active participant in tumor progression." (PMID 41584042, 2026). "Emerging evidence suggests that PLOD2 expression can be induced under hypoxic conditions and thus promote tumor progression, but the molecular mechanism has not been elucidated." (PMID 38233403, 2024). "Then, we clustered tumor cells using the FindClusters function with a resolution parameter of 0.3 in GSE159115, and we identified a tumor subtype, PLOD2 + SAA1 + ccRCC cells, which showed higher MECRGS scores, CNV scores, and stemness scores, suggesting a malignant status." (PMID 38951896, 2024). "Through mIF and IHC techniques applied to the Renji TMA cohort, we were able to identify the presence of PLOD2 + SAA1 + ccRCC cells and we found this tumor subclusters were related with high infiltration of CD163 + macrophages and Treg cells, indicating the establishment of an immunosuppressed TME." (PMID 38951896, 2024). "The PLOD family members (PLOD1, PLOD2, and PLOD3) were overexpressed in HNSCC tumor tissue." (PMID 36820030, 2023). "P4HA2 and PLOD2 are regulated by FOXA1, tumor growth factor-β (TGF-β), and hypoxia-inducible factor-α (HIF-1 α) to induce remodeling of extracellular matrix (ECM) and cancer cell stemness to drive tumor cell invasion and metastasis." (PMID 36826019, 2023). "Consistent with this, our IHC analysis of breast subcutaneous tumor tissues shows the expression of P4HA2 and PLOD2 in tissue derived from cells overexpressing RASSF1A is less pronounced compared to tissues derived from cells overexpressing RASSF1C and the vector backbone." (PMID 36826019, 2023). "These evaluations indicated that PLOD1, PLOD2, and PLOD3 might be high expressed in HNSCC tumor tissues compared with normal tissues (all p < 0.01)." (PMID 36820030, 2023). "Moreover, the results showed that the expression levels of LOXL2, PLOD2, MMP14 and SPOCK1 was higher whereas that of DCN was lower in tumor tissues compared with normal tissues." (PMID 36186418, 2022). "Hence, PLOD2 activation induced by HIF-1α is especially critical to ultimately increase fibrillar collagen formation and tumor stiffness." (PMID 36140753, 2022). "Hence, we found that not only PLOD1 but also PLOD2 and PLOD3 were abundantly expressed in tumor tissues." (PMID 35250490, 2022). "DeLong’s test showed that PLOD1 was superior to PLOD2 in predicting tumor and normal outcomes, but the test was not statistically significant (p = 0.148); PLOD1 was significantly superior to PLOD3 (p ≤ 0.01)." (PMID 35265665, 2021). "In the realm of cancer research, PLOD2 has been thoroughly explored in several studies and was confirmed to mediate hypoxia-induced cancer metastasis via collagen modification and ECM remodelling in primary tumours." (PMID 28507454, 2017). "This might be explained by the theory that co-activation of PLOD2 and HIF-α is essential for tumor cell invasion and migration." (PMID 28410212, 2017).